NECTIN1 (nectin cell adhesion molecule 1)
Diseases named in the same sentence as NECTIN1 in open-access papers (continued):
Sharing a sentence is not in itself a finding about the gene and the disease.
infection (continued). "The gD binding site is located exclusively within the N-terminal V-domain of nectin-1, validating previous predictions from in vitro binding and infection assays." (PMID 21980294, 2011). "HSV-1 is capable of developing an infection in HCE cells using a pH dependent entry process that involves primarily nectin-1 but also the HVEM and PILR-α receptors." (PMID 21139972, 2010). "We first demonstrated that HSV-1 can successfully enter and infect the HCE cell line, and that the infection process relies on the receptors nectin-1, HVEM, and PILR-α, located on the cell membrane." (PMID 21139972, 2010). "The result that average nectin-1 expression was reduced after the initial infection is an observation that requires further investigation." (PMID 21139972, 2010). "The differential use of these receptors is of importance for HSV entry of different cell types and infection of polarized cells, exemplified by nectin-1, which is of importance in infection of the vaginal mucosa." (PMID 16076403, 2005). "Notably, this modification also allowed limited infection of nectin-1-positive cells, enabling adapter-independent viral spread to some extent." (PMID 41403403, 2026). "However, infection through nectin-1 remained active and depended significantly on cell-surface glycosaminoglycans." (PMID 41403403, 2026). "We observed a high variability in susceptibility to oHSV1-FLT3L infection between the distinct cancer cell lines and found that there was a correlation between the inhibition of tumor cell growth and the expression of NECTIN2, ITGB6, and NECTIN1 genes." (PMID 40955425, 2025). "Thus, the productive infection of the keratinocytes induced an indirect increase in accessibility to nectin-1 as a possible alternative mechanism of spread." (PMID 39599904, 2024). "We demonstrated that the depletion of NECTIN1 could significantly enhance the infection of both biotypes and multiple genotypes of BVDV, including BVDV-1a, -1b, -1c, -1p, -1m, -1v, and -2a." (PMID 39570015, 2024). "To this end, we evaluated surface expression of nectin-1 during infection." (PMID 35604159, 2022). "Due to the loss of adhesion to the substrate at later time points in infection, it was not possible to examine nectin-1 immunofluorescence at later timepoints in this neuronal model." (PMID 33750985, 2021). "For example, the connections provided by nectin-1 subunits, which dimerize to link cells, are lost when gD downregulates the subunits in infected cells, thereby freeing up their partners in adjacent cells to allow infection." (PMID 29742155, 2018). "Mucosal epithelium may also serve as an HIV reservoir and as a source of tat and gp120, which disrupt AJs and expose nectin-1, leading to infection and spread of HSV-1 and -2." (PMID 24586397, 2014). "To investigate whether the major cell receptors for HSV-1 play a role in the increase of susceptibility of differentiated OLs to the infection, we monitored expression of HVEM, nectin-1 and 3-OS HS along the process of differentiation." (PMID 24551233, 2014). "Previous studies from our own and other labs reported the surprising finding that the soluble V domain of the herpes simplex virus type 1 (HSV-1) entry receptor nectin-1 can both block HSV infection of receptor-bearing cells and mediate infection of receptor-deficient cells." (PMID 22239829, 2012). "Thus, a prior infection by a HSV-1 strain can reduce the nectin-1 expression relative to uninfected cells." (PMID 21139972, 2010). "Thus nectin-1 appears downregulated on the cell surface during infection." (PMID 39599904, 2024). "Moreover, since gD and CD96 have similar affinity for nectin-1 a competition between the two ligands may occur during infection." (PMID 30759143, 2019). "Thus, nectin-1 was abundantly expressed just below HS-positive neuronal cilia, suggesting that the neuroepithelial infection preference of HSV-1 may reflect the availability of nectin-1 as well as HS." (PMID 23903843, 2013).
infection (continued). "This adapter facilitated the infection of ectopic CEA-expressing CHO–K1 cells and CEA-positive gastric cancer cells (MKN45) by a nectin-1-detargeted mutant virus (K-222/3NI)." (PMID 41403403, 2026). "HIV-1 Tat-induced disruption of epithelial junctions facilitates infection and spread of HSV-1 by liberating its otherwise sequestered gD receptor, nectin-1." (PMID 40018040, 2025). "Upon infection with the viral particles produced from each cell clone at an MOI of 1, we observed that the infected NECTIN1 knockout cell clones produced more infectious virus particles, irrespective of the origin of the virions." (PMID 39570015, 2024). "In this study, we engineered serum-free-adapted, suspension CHO cells to be permissive for HSV-1 entry and infection via expression of HVEM and/or Nectin-1 proteins." (PMID 37932360, 2023). "Our ex vivo infection studies of AD skin shaves imply that HSV-1 can overcome both barriers, the stratum corneum and the TJs, to reach its receptor nectin-1, which, as a component of adherens junctions, is located underneath TJs." (PMID 35969080, 2022). "It has been shown that asymmetric distribution of nectin-1, one of the HSV-1 receptors, contributes to the preferential infection of the apical surface of polarized epithelial cells by this virus." (PMID 35746762, 2022). "Isolated Epi-cDC2s support higher levels of infection than LCs in vitro, inhibited by acyclovir, but both MNP subtypes express similar levels of the HSV entry receptors nectin-1 and HVEM, and show similar levels of initial uptake." (PMID 33905459, 2021). "Upon T-VEC infection, cell viability gradually decreased in HVEM-KO cells, while it was preserved in Nectin-1-KO cells early after infection and Nectin-1-/HVEM-double-KO cells were almost insensitive." (PMID 34205379, 2021). "In the process of infection, the N-terminus of gD binds to the HVEM or nectin-1 and the C-terminus is opened from binding to N-terminus." (PMID 30799657, 2018). "It is notable that the whole gD footprint in nectin-1 overlaps extensively with the nectin-1 dimerization interface, which explains a novel mechanism of exploiting the host cell-adhesion functions by HSV for virus spread and infection." (PMID 28542478, 2017). "The structure of the gD/Nectin-1 complex also provides a frame to design of inhibitors that would block HSV entry and infection." (PMID 21980294, 2011). "Importantly, NECTIN1 also exhibited antiviral activity against classical swine fever virus (CSFV), Japanese encephalitis virus (JEV), and Zika virus (ZIKV) infections." (PMID 39570015, 2024). "Similarly, studies showed that nectin-1 is exposed in oral mucosal keratinocytes where the tight junctions were disrupted due to HIV infection, thereby increasing the rate of infection of the mucosa with HSV1." (PMID 39599904, 2024). "This phenomenon was demonstrated to be at the protein level only, as quantitative PCR analysis showed the nectin-1 transcription did not change at early time points post-infection." (PMID 39599904, 2024). "Consistently, HSV-1-GFP infection was also significantly mitigated by depletion of NECTIN1, whereas no obvious impact on infection with an irrelevant virus (VSV-GFP) was observed under the same treatment." (PMID 39570015, 2024). "Specifically, the absence of nectin-1 was observed in the foci of HSV1-GFP infection via immunofluorescence staining." (PMID 39599904, 2024). "HSV-1 uses several routes of entry to initiate infection of cells including HVEM (TNFRSF14), nectin-1, nectin-2, 3-O-sulfated heparan sulfate (3-OS-HS), paired immunoglobulin-like type 2 receptor (PILRα), non-muscle myosin heavy chain IIA (NMHC-IIA), and myelin-associated glycoprotein (MAG)." (PMID 37738264, 2023). "Notably, cell lines with a distinct expression of Nectin-1 (IGR-37, IGR-39, SK-MEL-3) were amongst those with the most pronounced reduction in viability upon T-VEC infection." (PMID 34205379, 2021).
infection (continued). "B16F10 cells lack nectin-1, the receptor for HSV-1, and are thus refractory to infection by HSV." (PMID 33177208, 2021). "We did not try to express murine nectin-1 to see if it was as effective in allowing for oHSV entry and infection." (PMID 32198420, 2020). "In the absence of nectin-1, wild type K562 cells were resistant to infection while K562-N1G cells became infected." (PMID 30759143, 2019). "Second, R-213 is detargeted from nectin-1 by virtue of the gD deletion, as shown by the lack of infection of J-nectin-1 cells." (PMID 28250120, 2017). "The pathway may rely on lymphocytes that cross the blood-brain barrier (BBB), on infection of endothelial cells of the BBB, or on nectin 1-positive cells from the CNS capturing membranes and cytoplasm from the surface of adjacent cells via a transendocytosis mechanism." (PMID 34061592, 2021). "By contrast, P. gingivalis did not degrade CDH1, DSC2, or NECTIN1 at 1 h after infection." (PMID 31697789, 2019). "Overexpression of nectin-1 in tumor cells is not described, but nectin-1 serves as an entry receptor for herpesviruses in human and mouse and therefore control of infection via CD96 expressed by NK cells may differ between species." (PMID 29868026, 2018). "To ensure that we were not using an inoculum so high as to overcome any effect the absence of nectin-1 may have on infection, we initially infected mice using a low inoculum of 1 x 103 IFU/mouse." (PMID 27486990, 2016). "We confirmed the efficient infection of N/TERT-1 cells by HSV-1 in culture as shown recently and demonstrated expression of the receptor nectin-1 on nearly all cells by flow cytometry (data not shown)." (PMID 37289055, 2023). "Interestingly, adapter-mediated infection relied on low pH-dependent endocytosis, similar to wild-type HSV-1 infection of nectin-1-expressing CHO cells, indicating that the adapter does not significantly alter the viral entry mechanism." (PMID 41403403, 2026). "This was evidenced by the fact that VSV/BVpv infection of BV-permissive Vero cells was inhibited in the presence of an anti-gD antibody, while VSV/BVpv infection of the BV-nonpermissive CHO-K1 cells was increased on expression of nectin-1." (PMID 38847539, 2024). "Whereas anti-nectin-1 mAb CK41 had no detectable effect, an anti-HVEM serum prevented infection, indicating that newly available HVEM may allow virus entry into saliva-stimulated B78H1 cells." (PMID 31581238, 2019). "Interestingly, the absence of nectin-1, but not HVEM, reduced efficiency of HSV-2 spread to the nerve system via both vaginal and intracranial routes of infection." (PMID 29342882, 2018). "Our findings suggest that receptor usage limited to nectin-1 does not significantly change the replication and spread of HSV-1 in the corneal epithelium during the early stages of the primary infection, and does not affect the capacity of the virus to spread to the TG." (PMID 23213272, 2012).
tumor (54 papers, 2007 to 2026). "NECTIN1 loss is associated with enhanced invasion, yet in some cancers, low NECTIN1 expression correlates with better outcomes, indicating tumor-type–specific roles that complicate generalization." (PMID 41008880, 2025). "We here observed rapid Nectin-1 cleavage in response to TT treatment in tumour cells, leading to cell surface loss of Nectin-1." (PMID 38891113, 2024). "Through integrative analysis of single-cell RNA sequencing data from 30 TNBC samples (106,132 cells), we identify key tumor expression metaprograms and uncover their interaction with an immunosuppressive dendritic-cell subset, a process associated with the NECTIN1-NECTIN4 axis." (PMID 41683914, 2026). "Whether the level of expression of nectin-1 in naturally occurring tumor cells affects their susceptibility to human NK cells remains to be determined." (PMID 30759143, 2019). "It was also demonstrated that the ectodomain shedding of transmembrane glycoproteins such as nectin-1 or nectin-4 by matrix metalloproteases (MMPs) or ADAMs (a disintegrin and metalloproteinases) causes a decrease in cell-cell interaction and is involved in tumor cell migration and invasion." (PMID 31419250, 2019). "CD96 belongs to the immunoglobulin superfamily and acts as a co-inhibitory receptor that competes with the co-stimulatory receptor CD226 for the shared ligands CD155 (PVR) and CD211 (NECTIN1), both of which are expressed on tumor and myeloid cells." (PMID 39811671, 2025). "Biomarkers should be identified and validated (e.g., tumor expression of nectin-1, PD-L1 status, or host interferon signature) to select patients most likely to have a response to oHSV therapy, enabling a more personalized approach." (PMID 40872965, 2025). "Since Nectin-1 appears to play an increasing role in tumor immune response, we studied its mechanism of action by analyzing NK-cell function." (PMID 37435061, 2023). "In different tumor contexts, such as that of pediatric and adult brain tumors, Nectin-1 was found upregulated." (PMID 37435061, 2023). "Pediatric tumor GSCs expressed significantly higher levels of HSV entry mediator nectin-1 (CD111) than adult GSCs, which inversely correlated with IC50." (PMID 37325516, 2023). "What level of Nectin-1 expression is actually required for tumor regression remains an open question." (PMID 34205379, 2021). "Altogether, Nectin-1 expression correlated with T-VEC induced tumor cell regression in vitro and in vivo, while respective expression of HVEM, STING, and cGAS did not predict response." (PMID 34205379, 2021). "To investigate the possible association between the expression of Nectin-1, HVEM, cGAS, and STING with the response to T-VEC injection in vivo, we analyzed tumor biopsies before treatment with immunohistochemical methods for the expression of these markers." (PMID 34205379, 2021). "The primary HSV entry receptor nectin-1 (CD111), an adhesion molecule, is expressed in significantly higher amounts in pediatric tumor cells compared to adults and displays sensitivity to the virus in vitro, requiring a substantially lower dose." (PMID 31970590, 2020). "This will need to be validated in clinical trials to determine if there is a specific threshold of nectin-1 required for a response and highlights the importance of obtaining and evaluating patient tumor tissue." (PMID 30224769, 2018). "Since the pediatric tumor cells expressed significantly more nectin-1 than the adult tumor cells and were more sensitive than the adult tumors, we sought to determine if expression levels of nectin-1 correlated with the sensitivity of the cells to the viruses." (PMID 30224769, 2018). "For other tumor cells that express either HVEM or nectin-1 alone or both of them, we found similar oncolytic effect of viruses derived from both HSV serotypes." (PMID 29765544, 2018).
tumor (continued). "Additionally, their study found a high nectin-1 expression in CAFs to correlate with the presence of perineural invasion, a higher tumor stage, and even localization." (PMID 40244005, 2025). "Human nectin-1, nectin-2, and nectin-3 are expressed by fibroblasts, epithelial cells, and neuronal cells, while human nectin-4 is mainly expressed during embryonic development and in tumor tissues." (PMID 36059705, 2022). "Nectin 1 ~ 3 is commonly enriched in normal adult tissues, while Nectin-4 was found to be specifically up-regulated in various tumors, having a significant role in tumor occurrence and development." (PMID 35953862, 2022). "Along this line, Nectin-1 could be important for the success of oncolytic herpes viruses in other tumor entities, which should be evaluated in further studies." (PMID 34205379, 2021). "However, our IHC staining and scoring protocol was stable and allowed reliable identification of low versus high Nectin-1 expressing tumor biopsies." (PMID 34205379, 2021). "Nectin-1 is an adhesion molecule and may be up-regulated in hypoxia to increase adhesion to vascular endothelial cells and facilitate tumor angiogenesis." (PMID 23450706, 2013). "The expression of nectin-1, rather than deficiencies in the cellular antiviral mechanisms, is a critical determinant of tumor cell susceptibility to HSV-1 and may serve as a predictor of therapeutic efficacy." (PMID 40698086, 2025). "Other tumor features, like T stage, metastasis, the location of the tumor, the grade of cellular differentiation, vascular and peri-neural invasion and mucinous histologic subtype, were not linked to nectin-1 expression." (PMID 37568798, 2023). "Whether NECTIN1 controls similar mechanisms in these tumor types remains to be determined." (PMID 36229674, 2022). "This may be related to the various expression basal lines of nectin-1 in different tumor cells." (PMID 36560800, 2022). "The correlation between inhibition of tumor cell growth and the expression of NECTIN2, ITGB6, and NECTIN1 genes warrants their further investigation as potential biomarkers for oHSV1-FLT3L therapy." (PMID 40955425, 2025). "The growth inhibitory effect was correlated to the expression of NECTIN1, NECTIN2, and ITGB6 by the tumor cell lines." (PMID 40955425, 2025). "This engineering contemporaneously allows de-targeting from endogenous HSV-1 entry receptors (i.e., HVEM, Nectin1) and re-targeting to HER2 as TAA model antigen to get tumor-restricted tropism." (PMID 38839891, 2024). "As expected from the combination of the spatial and scRNA sequencing data, we found positive correlations between the expression of INHBA and collective migration marker genes (CLDN4, NECTIN1, and DSG3) at the tumor-stroma interface." (PMID 35986012, 2022). "NECTIN1 and NECTIN4 are most strongly expressed in tumor cells, but NECTIN2 and NECTIN3 are also expressed in some lymphocyte cell types, while TIGIT is largely expressed in Tregs and exhausted CD4+ T cells." (PMID 35995947, 2022). "NK–tumor interactions included HLA-C/KIR2DL4, HLA-E/CD94 (KLD1), TIM3 (HAVCR2)/Galectin-9, CD96-PVR/Nectin1 and TIGIT-PVR/Nectin2." (PMID 33671917, 2021). "To determine if differential receptor expression contributed to this discrepancy, we analyzed these tumor cells by flow cytometry for cell surface expression of three known HSV receptors, HVEM, nectin-1 and nectin-2." (PMID 29765544, 2018). "The reported expression of nectin-1 was high in the tumor tissue compared to the adjacent non-cancerous tissue." (PMID 37568798, 2023). "Moreover, alongside the increasing TNM stage, tumor grade and Nottingham Prognostic Indicator (NPI), the expression of nectin-1 also increased." (PMID 37568798, 2023). "Nectin-1 and HVEM are ubiquitously expressed in human tissues and cells, thus mutants of gD and gB which are defective in binding to natural HSV-1 entry receptors are fused with ligands that show tumor-specific binding to permit for virus re-targeting." (PMID 35062322, 2022).